MDK (midkine)
Diseases named in the same sentence as MDK in open-access papers (continued):
Sharing a sentence is not in itself a finding about the gene and the disease.
prostate carcinoma (continued). "Since MDK is highly expressed in hepatocellular, gastric, colorectal and prostate cancers, the MDK inhibitor iMDK may be useful for treating non-pulmonary tumors as well." (PMID 23976985, 2013). "MDK expression in prostate cancer tissues was reported by one group." (PMID 18275606, 2008). "Furthermore, midkine expression was significantly increased in late stage prostate cancer, which coincides with previously reported high serum levels of TNFα in advanced prostate cancer." (PMID 18275606, 2008). "This study provides the first demonstration that midkine expression is induced by certain growth factors and cytokines, particularly TNFα, which offers new insight into understanding how midkine expression is increased in the late stage prostate cancers." (PMID 18275606, 2008). "Combination of MDK specific siRNA and chemotherapy may be a promising strategy for the late stage prostate cancers as shown by a recent study." (PMID 18275606, 2008). "In this study, we found that FBS induced MDK expression in the human prostate cancer LNCaP cells." (PMID 18275606, 2008). "Midkine expression is increased in the late stage prostate cancers." (PMID 18275606, 2008). "We identified that fetal bovine serum, some growth factors (epidermal growth factor, androgen, insulin-like growth factor-I, and hepatocyte growth factor) and cytokines (TNFα and interleukin-1beta) induced midkine expression in a human prostate cancer cell line LNCaP cells." (PMID 18275606, 2008). "Finally, to investigate whether GPC2 knockdown inhibited the malignancy of prostate cancer via MDK, we upregulated the expression of MDK in DU145 and PC-3 cells that were stably knocking down of GPC2, and performed functional assays." (PMID 39014225, 2024). "The rescue assay results in prostate cancer cells demonstrated that overexpression of MDK could attenuate GPC2 knockdown induced inactivation of PI3K/AKT signaling and partly reverse GPC2 knockdown induced inhibition of cell proliferation, migration, and invasion." (PMID 39014225, 2024). "Moreover, rescue experiments showed that overexpression of MDK could attenuate the inhibitory effect of GPC2 knockdown on prostate cancer proliferation, migration, and invasion." (PMID 39014225, 2024). "Furthermore, upregulation of MDK might lead to the stemness properties and cell survival of prostate cancer stem cells (Erdogan, Doganlar, Doganlar, Turkekul, & Serttas, 2017)." (PMID 32592428, 2020). "Therefore, it is possible that increased MDK expression the in late stage prostate cancers may be induced by increased systemic and/or local TNFα and other factors as identified in this study." (PMID 18275606, 2008). "In prostate cancer cells, TNF-α was found to up-regulate the NF-κB pathway, thereby inducing the transcription of MDK." (PMID 37240085, 2023). "MDK expression is induced by cytokines and growth factors such as TNF-α, which support prostate cancer cell survival." (PMID 37240085, 2023). "For instance, siRNA targeting midkine (a tumor promoting factor, MDK) (iMDK) induces cell cycle arrest at the S and G2/M phases, decreases p-Akt levels, and significantly up-regulates PTEN expression in CD133-positive population of prostate cancer cells." (PMID 39980929, 2025). "Our study provides a scientific basis for finding novel target therapy methods in prostate cancer and the GPC2/MDK/PI3K/AKT signaling axis might be promising therapeutic target." (PMID 39014225, 2024). "Two prostate cancer cell lines LNCaP and PC3 were studied for their expression of midkine." (PMID 18275606, 2008). "Konishi and coworkers first reported that MDK expression was positive in 86.3% of clinical prostate cancer, while normal prostate tissues were negative or showed only weak staining by immunohistochemical staining." (PMID 18275606, 2008).
prostate carcinoma (continued). "In this study, we found that the normal prostate tissues and early stage intermediate grade prostate cancers are negative or only weakly positive for MDK expression, while MDK expression is significantly increased in the late stage prostate cancers with higher Gleason scores." (PMID 18275606, 2008). "However, the biological role of MDK in prostate cancer has not been well addressed." (PMID 18275606, 2008).
liver cancer (11 papers, 2018 to 2025). An epithelial or non-epithelial malignant neoplasm that arises from the liver. "It has been reported that MDK also plays a role in the occurrence, development, metastasis, and prognosis of liver cancer." (PMID 37193028, 2023). "For example, MDK was recently reported to be a promising blood biomarker for the diagnosis of liver cancer." (PMID 31665503, 2020). "In BBCancer, we found MDK expression was higher in blood samples of liver cancer patients compared to blood samples of normal persons (fold change >1.5, adjusted P-value < 0.05)." (PMID 31665503, 2020). "In addition, many liver cancers are associated with HBV and HCV infections, and it has been suggested that MDK may have an impact on hepatitis-associated HCC." (PMID 37193028, 2023). "MYBL2 transfection in Huh7 liver cancer cells activated genes involved in cell proliferation, such as MDK (Midkine), an activator of AKT and ERK1/2 pathways." (PMID 31569678, 2019). "To further examine the expression of MDK in practical samples, we collected 36 pairs of liver cancer tissues and adjacent noncancer tissues." (PMID 35487917, 2022). "However, the efficacy of the combination of AFP + MDK, GPC3 + OPN has not been determined yet; therefore, significance of the combined use of these tumor markers in the diagnosis of liver cancer should be investigated in the near future." (PMID 34513063, 2021).
non-small cell lung carcinoma (11 papers, 2013 to 2025). A group of at least three distinct histological types of lung cancer, including non-small cell squamous cell carcinoma, adenocarcinoma, and large cell carcinoma. "In non-small-cell lung cancer, MDK derived from cancer-associated fibroblasts is capable of promoting radioresistance by enhancing glycolysis via Wnt/β-catenin activation." (PMID 40429950, 2025). "The aim of this study was to evaluate serum midkine (S-MK) both as a diagnostic and prognostic biomarker in non-small cell lung cancer (NSCLC)." (PMID 34272441, 2021). "The midkine inhibitor iMDK has shown anti-tumor efficacy in non-small cell lung cancer by blocking the PI3K-AKT pathway." (PMID 41339619, 2025). "Targeting the expression of MDK provides a new therapeutic approach for the treatment of MDK-expressing non-small cell lung cancers." (PMID 23976985, 2013). "Furthermore, one study found that MDK can promote phagocytic activity and lipid metabolism in macrophages, conferring a phenotype that promotes osimertinib resistance in metastatic non-small-cell lung cancer." (PMID 40429950, 2025). "In addition, TCGA data showed that high expression of MDK, MIF, and TGFBV1 is associated with poor prognosis in patients with non-small cell lung cancer." (PMID 40948762, 2025). "MDK plays an important role in non-small cell lung cancer progression and prognosis and may act as a convincing prognostic indicator for non-small cell lung cancer patients." (PMID 31992202, 2020). "In summary, we have determined that the MDK inhibitor iMDK suppresses non-small cell lung cancer expressing MDK in vitro and in vivo without harming normal cells." (PMID 23976985, 2013).
Alzheimer disease (10 papers, 2008 to 2025). A progressive, neurodegenerative disease characterized by loss of function and death of nerve cells in several areas of the brain leading to loss of cognitive function such as memory and language. "Disease‐related publications suggest accumulation of midkine in senile plaques and increased serum levels in patients with Alzheimer's disease, genetic variations associated with PD, and an influence on addictive behaviors." (PMID 35796185, 2022). "LDL receptor-related protein (LRP) is a receptor of midkine and pleiotrophin and it is genetically linked to Alzheimer’s disease." (PMID 28101734, 2017). "Midkine is known to exert neuroprotective effects in some of these pathologies including Alzheimer's disease and brain ischemia." (PMID 28044069, 2016). "Midkine was found to accumulate in senile plaques in the hippocampus of patients with Alzheimer's disease." (PMID 21223602, 2011). "Reflecting this accumulation, serum levels of midkine were increased in about half of patients with Alzheimer's disease." (PMID 21223602, 2011). "Midkine accumulates in senile plaques of patients with Alzheimer's disease, while it counteracts the cytotoxic effects of amyloid β-peptide and inhibits its oligomerization." (PMID 21223602, 2011). "Furthermore, the importance of mitochondrial dysfunction and other proteins, such as midkine and pleiotrophin, in the pathogenesis of Alzheimer’s disease is increasingly recognized." (PMID 39940772, 2025). "Thus, our structural and mouse model studies reveal a protective role of MDK in counteracting amyloid pathology in Alzheimer’s disease." (PMID 38883748, 2024). "Proteomic profiling of Alzheimer’s disease (AD) brains has identified numerous understudied proteins, including midkine (MDK), that are highly upregulated and correlated with Aβ since the early disease stage, but their roles in disease progression are not fully understood." (PMID 38883748, 2024). "In addition, MDK also accumulated in senile plaques in the hippocampus of patients with Alzheimer’s disease." (PMID 31175266, 2019). "Midkine and pleiotrophin are involved in neurodegenerative diseases such as Alzheimer’s disease." (PMID 28101734, 2017). "Midkine is expected to suppress the process leading to Alzheimer's disease." (PMID 21223602, 2011). "Thus, we performed further studies to understand the role of midkine during the development of Alzheimer's disease." (PMID 21223602, 2011). "Midkine, which has neuroprotective activity and neurite extension, expresses strongly in cerebral infarct and Alzheimer's disease." (PMID 18682710, 2008). "Therefore, midkine is likely to inhibit the process leading to the onset of Alzheimer's disease." (PMID 21223602, 2011). "Upregulated MDK and PTN expression has been found following CNS injury and neurodegenerative diseases, including ischemic stroke, Alzheimer's disease, and multiple system atrophy." (PMID 37269057, 2023). "However, some caution is required to state that enhancement of migration of microglias by midkine contributes to suppression of the disease progression, since there are reports that microglias are involved in inflammation in the brain, and in etiology of Alzheimer's disease." (PMID 21223602, 2011). "The accumulation of midkine in senile plaques does not necessary mean an involvement in the etiology of Alzheimer's disease." (PMID 21223602, 2011).
bladder cancer (10 papers, 2002 to 2025). "In bladder cancer cell lines, midkine mRNA expression was observed in all experimental cell lines, with the lowest expression observed in UMUC-3 cells." (PMID 37367056, 2023). "Many cancers have relatively high MDK expression in comparison to matched normal tissues, including bladder cancer." (PMID 36028490, 2022). "CD46 and midkine expression in bladder cancer cell lines have already been confirmed." (PMID 37367056, 2023). "Furthermore, MDK was detected in urine, and its high expression in urine might be correlated with worse prognosis in patients with bladder cancer." (PMID 29872508, 2018). "It quantifies four mRNAs which are overexpressed in bladder cancer: cycline-dependent kinase 1 (CDK1), homeobox A13 (HOXA13), midkine (MDK), and insulin-like growth factor-binding protein 5 (IGFBP5)." (PMID 30769831, 2019).
nasopharyngeal carcinoma (10 papers, 2018 to 2023). A carcinoma arising from the nasopharyngeal epithelium. "Additionally, the miRNA-9 levels in EVs were positively associated with overall survival, while midkine gene overexpression was positively correlated with poor prognosis in nasopharyngeal carcinoma patients." (PMID 35574333, 2022). "For instance, in nasopharyngeal carcinoma, increased exosomal miR-9 cargo inhibits angiogenesis by targeting MDK and through the PDK/AKT pathway." (PMID 37685891, 2023). "In nasopharyngeal carcinoma, exosomal miR-9 has been shown to target the MDK and PDK/AKT signaling pathway and inhibit the formation and migration of endothelial tubes." (PMID 35681531, 2022). "The findings of this study suggest that miR-9 and Midkine may be valuable as novel targets for the treatment of human nasopharyngeal carcinoma." (PMID 32823989, 2020). "The findings of this study suggest that miR-9 and MDK may be valuable as novel targets for the treatment of human nasopharyngeal carcinoma." (PMID 30001734, 2018). "Another study showed that nasopharyngeal carcinoma (NPC) cells secreted exosomes that enclose miR-9, which suppressed endothelial tube formation and migration by targeting MDK and modulating the PDK/AKT signalling pathway." (PMID 35326397, 2022). "Taken together, our data identify exosomal miR-9 derived from NPC cells inhibits angiogenesis by targeting MDK and regulating PDK/AKT pathway in nasopharyngeal carcinoma." (PMID 30001734, 2018). "For instance, tumor-derived EVs mediate the delivery of miRNA-9 to inhibit angiogenesis by targeting midkine gene and regulating the PDK/AKT pathway nasopharyngeal carcinoma." (PMID 35574333, 2022). "A Chinese group identified that exosomal miR-9 derived from nasopharyngeal carcinoma cells inhibits angiogenesis by targeting Midkine (a heparin-binding growth factor) and regulating the PDK/AKT pathway in nasopharyngeal carcinoma." (PMID 32823989, 2020). "High expression of MDK in NPC tumor samples is positively correlated with microvessel density, revealing the anti-angiogenic effects of exosomal miR-9 in the development of nasopharyngeal carcinoma." (PMID 32299469, 2020).
colorectal cancer (9 papers, 1999 to 2026). A primary or metastatic malignant neoplasm that affects the colon or rectum. "While serum MDK is widely recognized as a potential prognostic biomarker for colorectal cancer (CRC), its specific functional role and underlying mechanisms in CRC development are not fully understood." (PMID 42073635, 2026). "The functional polymorphism of MDK has been linked to the risk of cancer and the clinical results in advanced colorectal cancer." (PMID 40468625, 2025). "Although it was discovered that midkine (MDK) was increased in colorectal cancer and that nucleolin (NCL) was linked to DNA and RNA metabolism and proliferation, the precise relationship between the two has not yet undergone experimental verification and merits more investigation." (PMID 37228620, 2023). "This study shows that preoperative serum midkine level (S‐MK) is suitable as marker for screening of patients with colorectal carcinoma." (PMID 31984657, 2020). "The purpose of this study was to evaluate midkine, multipotential cytokine, and growth factor in colorectal cancer (CRC) stratified by tumor location." (PMID 22562257, 2012).
endometrial cancer (9 papers, 2012 to 2025). Primary or metastatic malignant neoplasm involving the endometrium (mucous membrane that lines the endometrial cavity). "The association of circulating midkine with lymph node metastasis has also been demonstrated in esophageal squamous cell carcinoma and in endometrial cancers." (PMID 22562257, 2012). "A subsequent study identified association between MDK and endometrial cancer, suggesting it could be included in a diagnostic panel for detection." (PMID 40429950, 2025). "The MDK-NCL signal is associated with suppressed immune activity in endometrial carcinoma." (PMID 39981249, 2025). "The ability of estrogen to promote MDK signaling is maintained in cancer cells as well, with MDK being an estrogen-induced gene in both lung and endometrial cancer cells." (PMID 40429950, 2025). "One study found that MDK was elevated in the serum of endometrial cancer patients relative to benign gynecological tumors, and tumors had higher MDK expression relative to healthy tissue." (PMID 40429950, 2025). "This highlights a potential challenge in using MDK as a biomarker in endometrial cancer, as upwards of 10% of reproductive-age women have endometriosis." (PMID 40429950, 2025). "Research using scRNA-seq and spatial transcriptomics highlighted MDK-NCL-dependent immune suppression in endometrial cancer." (PMID 40777026, 2025). "The MDK-NCL signaling network has been shown to promote the immunosuppressive environment and is associated with poor prognosis in endometrial carcinoma." (PMID 40725006, 2025). "Single-cell RNA sequencing has indicated that MDK may be able to mediate the communication of a malignant phenotype from endometrial cancer cells to endothelial cells via an MDK-NCL signal." (PMID 40429950, 2025). "Furthermore, preoperative serum concentrations of MDK correlated with both the lymph node metastasis status and the prognosis of endometrial cancer patients." (PMID 40429950, 2025). "The potential of MDK as a biomarker in endometrial cancer is a topic of debate." (PMID 40429950, 2025). "MDK inhibition via imatinib mesylate, a tyrosine kinase inhibitor, has been proposed as a mechanism by which the drug reduces endometrial cancer viability, with the addition of medroxyprogesterone acetate contributing to a further drop in both MDK and viability." (PMID 40429950, 2025). "This reduction of MDK in response to a progesterone treatment further supports a potential role for MDK as an estrogen-related gene and suggests a potential role for MDK in estrogen-driven women’s cancers such as endometrial cancer—a role that remains to be studied." (PMID 40429950, 2025). "However, MDK is frequently overexpressed in endometrial cancer tissues." (PMID 40429950, 2025). "Contradicting other findings, one study reported no elevation of MDK in endometrial cancer, instead observing increased levels in patients with endometriosis." (PMID 40429950, 2025).